IGFBP5 (insulin like growth factor binding protein 5)
Diseases named in the same sentence as IGFBP5 in open-access papers (continued):
Sharing a sentence is not in itself a finding about the gene and the disease.
atherosclerosis (8 papers, 2017 to 2025). A disease characterized by the build-up of fatty material and calcium deposition in the arterial wall resulting in partial or complete occlusion of the arterial lumen. "The expression of IGFBP5 was induced in the skeletal muscle of male ApoE−/− mice, an atherosclerosis model, using adeno-associated virus, resulting in elevated circulating IGFBP5 levels." (PMID 40729024, 2025). "IGFBP5 has been implicated in processes relating to smooth muscle proliferation and migration in atherosclerosis research." (PMID 39408698, 2024). "The evidence suggests that IGFBP5 may play a role in the pathogenesis of atherosclerosis, which is the leading cause of cardiovascular disease." (PMID 39337683, 2024). "The role of IGFBP-5 in both atherosclerosis and fibrosis may be linked to the induction of cellular senescence." (PMID 32194505, 2020). "Thus, the association of IGFBP-5 with atherosclerosis may indicate a direct stimulatory effect of IGFBP-5 on smooth muscle cell proliferation and plaque formation." (PMID 30061864, 2018). "To elucidate the exact role of IGFBP5 in atherosclerosis, we overexpressed IGFBP5 in the classic atherosclerosis mouse model, ApoE−/− mice." (PMID 40729024, 2025). "The function of IGFBP5 within the context of atherosclerosis remains a subject of considerable debate." (PMID 40729024, 2025). "The resultant data unequivocally suggested that IGFBP5 exacerbates atherosclerosis in these models, manifesting primarily as accelerated plaque formation." (PMID 40729024, 2025). "Analysis revealed that IGFBP5 overexpression led to a marked escalation in the total surface area occupied by atheroma on the aortic walls, indicative of exacerbated atherosclerosis." (PMID 40729024, 2025). "IGFBP-5 is known to bind to ECM components PAI-1 and osteopontin, which have both been found in atherosclerotic plaques and have been shown to promote atherosclerosis in loss of function studies." (PMID 32194505, 2020). "The present study aims to confirm the role and mechanism of IGFBP5 in atherosclerosis." (PMID 40729024, 2025). "IGFBP5 promotes atherosclerosis in ApoE−/− mice through the phenotypic transformation of VSMCs." (PMID 40729024, 2025). "In addition, the levels of IGFBP5, which are involved in the pathogenesis of atherosclerosis, significantly increased in patients with vitiligo." (PMID 39337683, 2024). "Previous study discovered that IGFBP5 takes part in the progression of atherosclerosis." (PMID 35178407, 2021). "IGFBP5 (insulin like growth factor binding protein 5) is epigenetically silenced by H3K27me3 in advanced atherosclerotic plaques, suggesting that targeting the H3K27me3/IGFBP5 pathway may provide novel therapeutics for atherosclerosis." (PMID 33996893, 2021). "IGFBP-5 may play a role in the pathogenesis of atherosclerosis, which is a process of inflammatory tissue remodeling within the matrix of the arterial wall that is the top cause of cardiovascular disease and aging-related mortality in humans." (PMID 32194505, 2020). "These staining patterns suggest that locally produced FXa in VSMCs and inflammatory cells might induce IGFBP-5 expression, resulting in the chronic inflammation and cellular senescence in human atherosclerosis." (PMID 29215061, 2017). "Thus, the precise function of IGFBP5 in atherosclerosis remains shrouded in ambiguity, lacking definitive elucidation or targeted examination." (PMID 40729024, 2025).
cognitive decline (8 papers, 2018 to 2025). "IGFBP5 is elevated in AD mice and higher levels associate with faster cognitive decline in AD patients." (PMID 38155736, 2023). "Studies have shown that IGFBP5 was associated with faster cognitive decline and was found to increase in the brains, cerebrospinal fluid, and animal models of AD." (PMID 37434738, 2023). "Enhanced levels of Insulin-like Growth Factor Binding Protein 5 (IGFBP-5) are associated with a faster rate of cognitive decline in Alzheimer’s disease (AD)." (PMID 35513854, 2022). "Further analysis of brain samples proteomes demonstrated that higher IGFBP5 protein level correlates with more rapid age-associated cognitive decline." (PMID 33673334, 2021). "In contrast, Rapid Decline showed increased β-amyloid (bA), glial and inflammatory markers (CD44, PLXNB1), and stress- and mitochondrial-related proteins (GSTP1, AK4, HSPB2, FBXO2, IGFBP5), which have been associated with neurodegeneration and cognitive decline in AD." (PMID 40799531, 2025). "Together with this core variable set, either MIR132, beta-amyloid, TAR DNA binding protein 43 (TDP-43), IGFBP5, or histone coacetylation modules could explain the mediation of AD-PRS to cognitive decline." (PMID 30349450, 2018). "Notably, the link between IGFBP5 expression and cognitive decline was not fully explained by AD, Lewy body and TDP-43 pathologies." (PMID 33673334, 2021).
colorectal cancer (8 papers, 2010 to 2026). A primary or metastatic malignant neoplasm that affects the colon or rectum. "IGFBP-5 has also been implicated in different types of cancers such as breast, ovarian, and colorectal cancer as well as in wound healing and tissue regeneration." (PMID 30374330, 2018). "Increased expression of IGFBP3 in RCC (and also in lung and colorectal cancer) was associated with inferior overall survival, while IGFBP5 expression had no apparent impact on prognosis in RCC." (PMID 39516665, 2024). "We inferred that other published miR-140 targets, such as ADAMTS5 and IGFBP5 in colorectal cancer, Pin1 in liver cancer, and IGF2BP1 in cervical cancer, which are associated with tumor migration and invasion, may contribute to these GC cell phenotypes." (PMID 28818100, 2017). "Indeed, while Igfbp5 is up regulated in adenomas from ApcMin/+ mice, it moves in the opposite direction in human colorectal cancers and cancer cell lines." (PMID 20459814, 2010).
liver fibrosis (8 papers, 2010 to 2025). "The aim of this study was to investigate the role of IGFBP5 in liver fibrosis by employing both gain and loss of function approaches." (PMID 20163708, 2010). "On the other hand, senescence in activated HSC was associated with impediment of liver fibrosis, leaving the role of IGFBP5 in the development of senescence in liver fibrogenesis opened for further inquiries." (PMID 20163708, 2010). "Lowering IGFBP5 expression may, therefore, not only impair the development of liver fibrosis but also reduce the risk of tumour formation." (PMID 20163708, 2010). "Pdgfb overexpression alone has been reported to induce liver fibrosis, while IGFBP5 is known to promote the survival of activated HSCs and myofibroblasts and to increase the expression of profibrotic genes, thereby contributing to liver fibrosis." (PMID 40810103, 2025). "The efficacy of targeting IGFBP5 in the intervention of liver fibrosis was further verified in the BDL model." (PMID 38092723, 2023). "BRG1 deletion in HSCs down-regulated whereas BRG1 over-expression in HSCs up–regulated IGFBP5 expression in vivo in different models of liver fibrosis." (PMID 38092723, 2023). "In contrast to the variability we see with primary fibroblasts, IGFBP-5 silencing was shown to consistently affect the survival of hepatic stellate cells in liver fibrosis due to increased cell apoptosis." (PMID 30374330, 2018). "Further, IGFBP-5 expression is increased in liver fibrosis in vivo and during hepatic stellate cell (HSC) transdifferentiation in vitro." (PMID 30374330, 2018). "In order to investigate a potential role of IGFBP5 in liver fibrosis, we developed methods to modulate its expression in LX2 cells." (PMID 20163708, 2010). "In that case the inhibition of IGF1 signalling by IGFBP5 would impair the pathogenesis of liver fibrosis." (PMID 20163708, 2010). "This strong induction of IGFBP5 expression was confirmed during the development of liver fibrosis in the Mdr2-/- mice, a well established animal model of liver fibrosis." (PMID 20163708, 2010). "We demonstrated that IGFBP5 expression strongly increased during development of liver fibrosis in Mdr2-/- mice." (PMID 20163708, 2010). "Since IGFBP5 has been shown to promote fibrosis in other tissues, the aim of this study was to investigate its role in the progression of liver fibrosis." (PMID 20163708, 2010). "Together, these data suggest that BRG1 might program HSC-myofibroblast transition and liver fibrosis by activating IGFBP5 transcription." (PMID 38092723, 2023). "Furthermore, IGFBP is involved in the evolution of liver fibrosis, where an increase in IGFBP5 likely leads to a higher production of collagen type I in fibroblasts and enhanced tissue fibrosis." (PMID 36836704, 2023). "Intriguingly, IGFBP5 is found to be most significantly altered by BRG1 deficiency, able to rescue myofibroblast phenotypes from BRG1 deficiency, and correlative/causal to liver fibrosis." (PMID 38092723, 2023). "Because VDR possesses potent antifibrotic activities in the liver, it is tempting to speculate that IGFBP5 might regulate liver fibrosis by functioning as an inhibitor of VDR." (PMID 38092723, 2023). "Its effect on these pro-fibrotic genes in a model for activated HSC indicates that IGFBP5 may also have a direct effect on the ECM deposition in liver fibrosis." (PMID 20163708, 2010). "As changed expression of these markers could further establish the (pro-fibrotic) role of IGFBP5 in liver fibrosis, we examined its influence on their expression in LX2 cells." (PMID 20163708, 2010). "The observed effects of IGFBP5 may therefore be due to its role in IGF1 signalling - that is to its disturbance of the IGF1 axis observed in liver fibrosis." (PMID 20163708, 2010). "The next series of experiments were performed to determine the role of IGFBP5 in HSC-myofibroblast transition and liver fibrosis." (PMID 38092723, 2023).
liver fibrosis (continued). "On the contrary, IGFBP5 knockdown suppressed HSC-myofibroblast transition in vitro and mollified liver fibrosis in mice." (PMID 38092723, 2023). "In the canonical pathway for hepatic fibrosis/hepatic stellate cell activation, COL3A1, FGFR1, and IGFBP5 (P<0.01) were involved, which indicates similarity to the biological pathways already described in ULs." (PMID 23483937, 2013). "We have previously shown that IGFBP5 expression was strongly upregulated during HSC transdifferentiation in vitro and during development of liver fibrosis in vivo." (PMID 20163708, 2010). "The presence of IGFBP5 in this animal model and in patients with HCC or CC suggests that, in addition to a role in the pathogenesis of liver fibrosis, IGFBP5 may also contribute to tumour formation." (PMID 20163708, 2010). "As IGFBP5 impairs the binding of IGF1 to the cell-surface receptor IGF1R, its increased expression in activated HSC and myofibroblasts may reduce IGF1 signalling and, thus, promote liver fibrosis." (PMID 20163708, 2010).
bladder cancer (6 papers, 2017 to 2022). "This suggested that both fibulin-3 and IGFBP5 can be used as biomarkers for bladder cancer and are associated with an aggressive tumor behavior." (PMID 35473807, 2022). "Moreover, an interesting finding in that study was that fibulin-3 knockdown in a murine model of bladder cancer was associated with decreased expression of insulin-like growth factor-binding protein-5 (IGFBP5)." (PMID 35473807, 2022). "In this study, both LAT1 and IGFBP-5 were highly expressed in T24 bladder cancer cells." (PMID 31992742, 2020). "Our results suggest that IGFBP5 expression could be used in this way in the bladder cancer setting." (PMID 28882129, 2017). "It quantifies four mRNAs which are overexpressed in bladder cancer: cycline-dependent kinase 1 (CDK1), homeobox A13 (HOXA13), midkine (MDK), and insulin-like growth factor-binding protein 5 (IGFBP5)." (PMID 30769831, 2019).
fibrosis (6 papers, 2008 to 2020). the formation of excess fibrous connective tissue in an organ or tissue in a reparative or reactive process. "In comparison to the pronounced effects of adenovirally expressed IGFBP-5 in vitro using human primary lung fibroblasts and ex vivo using human lung and skin tissues in fibrosis, the effects of transgenic expression of human IGFBP-5 in vivo were modest." (PMID 33396956, 2020). "Both IGFBP-3 and IGFBP-5 induce dermal fibrosis with IGFBP-5 exerting a more drastic phenotype than IGFBP-3." (PMID 19088866, 2008). "Importantly, both IGFBP3 and IGFBP5 contribute to extracellular (ECM) deposition in IPF and promote fibrosis in human skin maintained in organ culture, demonstrating direct relevance to the human disease." (PMID 32210969, 2020).
Insulin resistance (6 papers, 2020 to 2022). Increased resistance towards insulin, that is, diminished effectiveness of insulin in reducing blood glucose levels. "As confirmed by protein chip analyses, KY19334 decreased the expression levels of various adipokines such as angiopoietin‐3, DPP4, IGFBP‐5, leptin, resistin and PAI‐1, which are implicated in obesity‐related insulin resistance." (PMID 35384342, 2022). "The induction of VPS8, POLRMT, and IGFBP5 GPs at the end of 4th week during 4-week intermittent fasting preceded the significant reduction in insulin resistance estimated by HOMA-IR that occurred 1 week after 4-week intermittent fasting." (PMID 33110154, 2020). "Furthermore, miR-143-3p has been established to target IGF2R along with IGFBP5 thus possibly participates in insulin resistance reported in MetS." (PMID 34485272, 2021). "A decrease in IGFBP5 level may be associated with the pathogenesis of type 2 diabetes, and decreased GLUT4 expression may be one of the mechanisms by which IGFBP causes insulin resistance." (PMID 35643455, 2022).
Obesity (6 papers, 2015 to 2022). Accumulation of substantial excess body fat. "This suggests that IGFBP5 is protective against obesity and glucose metabolism impairment, but the specific role of hypothalamic IGFPB5 in metabolic control is unknown." (PMID 33202914, 2020).
osteoporosis (6 papers, 2008 to 2025). A condition of reduced bone mass, with decreased cortical thickness and a decrease in the number and size of the trabeculae of cancellous bone (but normal chemical composition), resulting in increased fracture incidence. "One of the two downregulated genes, IGFBP5 (insulin-like growth factor binding protein 5), is a key regulator of osteogenic differentiation, and agents that antagonize its expression have been shown to promote osteoporosis." (PMID 36992820, 2023). "Because microRNA-mediated silencing of IGFBP5 has been shown to promote osteoporosis, it is possible that attenuated expression of this gene in parathyroid adenomas could contribute to bone mineral density loss in PHPT in addition to the direct osteoclastic effects of PTH." (PMID 36992820, 2023). "So, IGFBP‐3 and IGFBP‐5 decrease in LLIs could be related to both sarcopenia and osteoporosis." (PMID 35932462, 2022).
periodontitis (5 papers, 2017 to 2025). An acute or chronic inflammatory process that affects the tissues that surround and support the teeth. "On the contrary, in periodontitis (PD) caused by porphyromonas gingivalis (Pg), ApoVs derived from Mφ were found enriched with miR-143-3p, targeting insulin-like growth factor-binding protein 5 (IGFBP5), thereby disrupting periodontal bone homeostasis." (PMID 40141469, 2025). "These discoveries further confirmed that loss of IGFBP5 impaired MSC function in periodontitis." (PMID 28962660, 2017). "Considering the fact that IGFBP-5 seems to be the only IGFBP tested in animal models of periodontitis, it would be a promising candidate for future clinical trials in addition to IGF-1 and IGF-2." (PMID 34940355, 2021). "In a preliminary study, insulin-like growth factor binding protein 5 was injected locally to promote periodontal tissue regeneration in a mini-pig model of periodontitis." (PMID 31900200, 2020). "The swine model of periodontitis was used to investigate the functions of IGFBP5 for periodontal regeneration and its anti-inflammation effect." (PMID 28962660, 2017). "In swine models of periodontitis, locally applied IGFBP-5 improved PD, CAL and new bone formation." (PMID 34940355, 2021). "Our findings provide insight into the mechanism underlying the activated capacities of MSCs, identified IGFBP5 as a potential cytokine for improving tissue regeneration and periodontitis treatment independent of exogenous MSCs, and suggest that IGFBP5 has potential application in the dental clinic." (PMID 28962660, 2017). "Our results identified a potential cytokine, IGFBP5, for improving tissue regeneration and periodontitis treatment in a manner independent of exogenous MSCs." (PMID 28962660, 2017). "Thus, in this study, we investigated the possibility of IGFBP5 protein application as a method of treatment for periodontitis independent of exogenous MSCs." (PMID 28962660, 2017). "However, the function of IGFBP5 protein in the regulation of MSCs in an inflammatory niche and whether it could promote periodontal tissue regeneration in periodontitis, especially independent of exogenous MSCs, is still not clear." (PMID 28962660, 2017).
thyroid cancer (5 papers, 2013 to 2024). "In papillary thyroid carcinoma (PTC), the most common form of thyroid cancer, IGFBP-5 expression is targeted by miR-204-5p, in contrast with the alternate precursor product, miR-204-3p, which was noted earlier as targeting IGFBP-2 in glioma." (PMID 35597813, 2022). "Again, this observation is consistent with IGFBP-5 being a miR-24-3p target in thyroid cancer." (PMID 35597813, 2022). "On the other hand, some of the genes determining variation in TSH levels are also known (oncogenic) genes in thyroid cancer such as MBIP, IGFBP5 and B4GALNT365–67." (PMID 38291025, 2024).
Arthritis (4 papers, 2009 to 2023). Inflammation of a joint. "Upregulation of IGFBP-5 has been related to increased proteo-lysis in muscle wasting induced by experimental arthritis, senescence and disuse." (PMID 37762414, 2023). "In dogs with arthritis, active forms of C1r and C1s, along with reduced concentrations of IGFBP-5, IGFBP-3 and IGF-1, were present in their synovial fluid." (PMID 38002958, 2023). "Additionally, elevated IGFBP-5 levels have been reported in muscle wasting induced by chronic inflammatory diseases, such as arthritis." (PMID 37762414, 2023). "Similarly, different anti-inflammatory treatments blocked the increase of IGFBP-5 in animal models of arthritis, reducing muscle wasting." (PMID 33375628, 2020).
diabetic kidney disease (4 papers, 2022 to 2024). Progressive kidney disorder caused by vascular damage to the glomerular capillaries, in patients with diabetes mellitus. "Since several studies performed so far have demonstrated the diverse effects of IGFBP5 in the regulation of cell function, our data implied that IGFBP5 might perform as an important therapeutic agent for disorders in humans, including diabetic nephropathy and CLI." (PMID 38886900, 2024). "In addition to tumours, elevated IGFBP5 levels were detected in diabetic kidney disease (DKD) mice." (PMID 38886900, 2024). "Additionally, a recent study reported a significant upregulation of IGFBP5 levels in diabetic kidney disease (DKD), although the exact function of IGFBP5 and its role in DKD remains elusive." (PMID 37762544, 2023).